CRP (C-reactive protein)
Diseases named in the same sentence as CRP in open-access papers (continued):
Sharing a sentence is not in itself a finding about the gene and the disease.
Pyoderma (2 papers, 2021 to 2023). Any manifestation of a skin disease associated with the production of pus. "After the first dose, gangrenous pyoderma had greatly improved and CRP decreased to 6.19 mg/dl." (PMID 34093563, 2021).
radiation pneumonitis (2 papers, 2020). Inflammation of the lung due to harmful effects of ionizing or non-ionizing radiation. "Inflammatory biomarker C-reactive protein (CRP) has also been shown to be an effective indicator of possible radiation pneumonitis in humans which was also observed as more than 6 fold increase of the protein in saline treated animals." (PMID 33343356, 2020). "The following four independent risk factors for AE were identified in univariate analysis: non-advanced age (<75 years), increased C-reactive protein level (≥0.3 mg/dl), adjuvant chemotherapy and ≥ Grade 2 radiation pneumonitis." (PMID 32363376, 2020).
reactive hemophagocytic syndrome (2 papers, 2021 to 2024). "CRP: C-reactive protein, PCT: Procalcitonin, TNF: Tumor-Necrosis Factor, H-Score for reactive hemophagocytic syndrome estimates the risk for having reactive hemophagocytic syndrome." (PMID 38557873, 2024).
rotator cuff tear (2 papers, 2019 to 2020). "Association between high-sensitive C-reactive protein and rotator cuff tear in relation to age." (PMID 32040493, 2020). "The studied variables were demographic, physical, social, metabolic, comorbidity, hs-CRP, and pain on a visual analog scale (VAS) factors, as well as those related to rotator cuff tear (RCT)." (PMID 31699076, 2019).
RSV bronchiolitis (2 papers, 2022 to 2025). "In patients with RSV bronchiolitis, it is worth mentioning that elevated CRP levels were associated with prolonged length of hospital stay." (PMID 35655792, 2022). "However, it was shown that patients with RSV bronchiolitis, bronchopneumonia, and RSV pneumonia had elevated levels of CRP along with higher white blood cells (WBC) count and erythrocyte sedimentation rate (ESR) which all indicate bacterial coinfection." (PMID 35655792, 2022).
soft tissue tumors (2 papers, 2018 to 2020). "The following five simple clinical characteristics or laboratory data: large tumor size (≥ 5.6 cm), high WBC count (≥ 5700/μL), low Hb count (≤ 12.4 g/dL), high CRP level (≥ 0.17 mg/dL), and high LDH level (≥ 240 IU/L) can be useful for predicting malignancy of soft tissue tumors." (PMID 32183216, 2020).
spondylolisthesis (2 papers, 2020 to 2025). A condition in which there is forward displacement of a vertebral bone over the on below it. "The MLP model results indicate that a history of lumbar spine trauma and herniation calcification are the most important features affecting the prediction outcome, contributing the most to the prediction of persistent pain, followed by spondylolisthesis, ESR, Pfirrmann Grading, and CRP." (PMID 40772257, 2025).
stomatitis (2 papers, 2018 to 2022). Inflammation of the oral mucosa due to local or systemic factors. "In the other case, adverse events included malaise, peripheral neuropathy, cheilitis, stomatitis, elevated CRP level and dysphagia." (PMID 35949598, 2022). "And between ‘stomatitis’ and ‘CRP’, more than 7 words take place." (PMID 30396345, 2018). "Of these five pairs, stomatitis-CRP pairs are much less common than the other pairs." (PMID 30396345, 2018). "This case may be regarded as an error of this methodology, but the closely related stomatitis and CRP may not be the subject of full-scale research." (PMID 30396345, 2018).
structural epilepsy (2 papers, 2024 to 2026). A type of epilepsy that is conceptualized as having a distinct structural brain abnormality that has been demonstrated to be associated with a substantially increased risk of epilepsy in appropriately designed studies. "In contrast, the C reactive protein concentration was abnormal only in dogs with cluster seizures due to idiopathic epilepsy and structural epilepsy." (PMID 39330787, 2024). "The CRP concentration has been investigated in dogs diagnosed with idiopathic (IE) or structural epilepsy (SE)." (PMID 39330787, 2024). "In conclusion, in the absence of other concurrent inflammatory diseases, the blood CRP concentration and NLR might be considered as potential non-specific markers and used in the diagnostic approach of dogs with structural epilepsy or cluster seizures in dogs with idiopathic epilepsy." (PMID 39330787, 2024). "Furthermore, we found that a half of the dogs diagnosed with either neoplasia or an inflammatory intracranial disease included in the SE group had an abnormal basal blood CRP value, similar to a previous report in which 62% of dogs with structural epilepsy had a higher blood CRP concentration." (PMID 39330787, 2024). "Both the CRP concentration and the NLR might be considered feasible non-specific markers of the neuroinflamation involved in epileptogenesis and might be used in the diagnosis of and therapeutic approach to cluster seizures in dogs with idiopathic epilepsy and in patients with structural epilepsy." (PMID 39330787, 2024).
sudden hearing loss (2 papers, 2020 to 2021). "Although C-reactive protein/albumin ratio was found to be lower in sudden hearing loss patients who responded to treatment compared to those who did not, the difference between two groups was not statistically significant." (PMID 30522831, 2020).
systemic amyloidosis (2 papers, 2012 to 2018). "The human pentraxin proteins, serum amyloid P component(SAP) and C‐reactive protein (CRP) are important in routine clinical diagnosis, SAPfor systemic amyloidosis and CRP for monitoring the non‐specific acute phaseresponse." (PMID 22867744, 2012). "CRP assay is one of the most widely used clinical chemistry tests and SAP scintigraphy has transformed understanding and optimal management of systemic amyloidosis." (PMID 30459761, 2018).
systolic heart failure (2 papers, 2017 to 2022). Heart failure caused by abnormal myocardial contraction during systole leading to defective cardiac emptying. "As compared to CRP, CRPv was a more sensitive and specific tool for the identification of patients at risk for developing severe systolic heart failure." (PMID 35054095, 2022). "Past studies proved that an elevation in CRP levels is associated with a reduced diastolic left ventricular (LV) function as well as systolic heart failure in the setting of STEMI." (PMID 35054095, 2022). "Recently, it was shown in a small cohort of 30 patients with systolic heart failure and acute decompensation; the administration of IL-1 blocker, anakinra reduced the inflammatory burden as shown by reduced C-reactive protein levels within 72 h." (PMID 28674538, 2017).
T-cell acute lymphoblastic leukaemia (2 papers, 2024 to 2025). "Composite indices such as the C-reactive protein/albumin ratio (CAR), the CRP × fibrinogen/albumin ratio (CFA), and the modified Glasgow Prognostic Score (mGPS) integrate these parameters, although their prognostic role in T-cell acute lymphoblastic leukaemia (T-ALL) remains underexplored." (PMID 41586228, 2025).
Thrombophlebitis (2 papers, 2018 to 2021). Inflammation of a vein associated with venous thrombosis (blood clot formation within the vein). "CRP was measured in 20 patients (40%) with severe thrombophlebitis: the mean CRP at the time of presentation was 60 (range: 3 to 169) mg/L." (PMID 34666737, 2021). "This reveals that CRP increased significantly in the acute stage of thrombophlebitis." (PMID 29849699, 2018).
thyroid nodule (2 papers, 2023). A small circumscribed mass in the THYROID GLAND that can be of neoplastic growth or non-neoplastic abnormality. "People with thyroid nodules can have elevated CRP levels, and a recent study revealed that a CRP increase is linked to thyroid nodules." (PMID 37873776, 2023).
tongue cancer (2 papers, 2017 to 2021). A malignant neoplasm affecting the tongue. "Nevertheless, it remains unclear whether the effect of CRP on the occurrence of tongue cancer is a causal relationship." (PMID 34386016, 2021). "In tongue cancer, CRP elevation (CRP ≥ 5.0 mg/L) showed a strong relationship with advanced pathological tumor status (p < 0.001) and correlated with advanced pathologic nodal status (p = 0.027) and advanced tumor stage (p = 0.021)." (PMID 28209200, 2017).
tracheobronchitis (2 papers, 2008 to 2023). Inflammation of the tracheobronchial tree. "A single level of CRP and PCT has been evaluated to differentiate ventilator-associated tracheobronchitis from VAP." (PMID 37893050, 2023).
treatment resistant depression (2 papers, 2021 to 2023). Unipolar depression that does not respond to commonly used treatments, typically defined as lack of response to at least two appropriate antidepressant treatments. "Patients with treatment-resistant depression (TRD, n = 28) presented significantly lower levels of SC and CAR, and higher levels of mBDNF and CRP than controls (n = 30)." (PMID 34421705, 2021).
trichomoniasis (2 papers, 2017 to 2022). An infection that is caused by Trichomonas. "During lactation, vaginal trichomoniasis was associated with an elevated CRP whereas vaginal Mobiluncus and eosinophil counts were associated with lower CRP and/or lower odds of an elevated CRP." (PMID 28571565, 2017). "Also, the positive association detected between trichomoniasis and CRP in lactation extends the findings of a systemic inflammatory response measured through CRP and granulocyte-macrophage colony-stimulating factor found in pregnant women with vaginal trichomoniasis." (PMID 28571565, 2017).
tricuspid insufficiency (2 papers, 2022 to 2023). "Similar manipulation was performed for CRP levels and tricuspid insufficiency, which yielded a correlation coefficient of -0.118 and a p value of 0.519." (PMID 37168408, 2023).
tubercular meningitis (2 papers, 2021 to 2025). "Among a cohort of adults with tuberculous meningitis, including 83% living with human immunodeficiency virus, we found that baseline C-reactive protein ≥40 mg/L independently predicts 3 times higher odds of severe disability or death at 8 weeks of antituberculous therapy." (PMID 40581751, 2025).
tubular adenoma (2 papers, 2016 to 2021). A usually polypoid neoplasm arising from the glandular epithelium. "In addition, high levels of circulating CRP (>2.95 mg/L) was inversely associated with risk of tubular adenomas in the CLUE II cohort." (PMID 27608842, 2016). "The PLR and CRP values were significantly higher in the tubular adenoma group than in the tubulovillous adenoma group." (PMID 34001040, 2021). "The results showed that in the tubular adenoma group, the platelet counts and CRP levels were higher than those in the tubulovillous adenoma group and the lymphocyte counts were lower than those in the tubulovillous adenoma group, but the differences were not statistically significant." (PMID 34001040, 2021).
Type A Aortic Dissection (2 papers, 2022 to 2025). "One example of this is one of the models that combined D-dimer, CRP, and MMP-9 to predict 1-year mortality in type A aortic dissection patients." (PMID 39910669, 2025).
uveal melanoma (2 papers, 2018 to 2021). A melanoma derived from melanocytes of the uveal tract. "In Patients treated with uveal melanoma liver metastases treated with transarterial chemoperfusion, lower pretreatment values of CRP, SII and ALT were independent prognostic factors associated with prolonged overall survival suggesting a role of systemic inflammation in this setting." (PMID 34051707, 2021).
Vertigo (2 papers, 2012 to 2023). An abnormal sensation of spinning while the body is actually stationary. "Therefore, CRP has progressively made BPPV the most successfully treatable cause of vertigo." (PMID 22518162, 2012).
vesicoureteral reflux (2 papers, 2009 to 2026). Abnormal flow of urine from the urinary bladder back into the ureters. "The secondary outcomes were the associations of PCT, CRP, and WBC with vesicoureteral reflux (VUR)." (PMID 42195064, 2026).
VEXAS syndrome (2 papers, 2022 to 2024). An adult-onset inflammatory disease that affects only males and is caused by somatic, not germline, mutations. "Due to persistently elevated CRP levels and the suspicion of VEXAS syndrome, genetic testing was conducted." (PMID 39251478, 2024). "Both CRP and neutrophil counts were elevated when VEXAS syndrome was active." (PMID 36544501, 2022).
visuospatial impairment (2 papers, 2019 to 2025). Impairment of visuospatial functioning. "A previous study on the role of inflammation in age-related cognitive dysfunction showed that those with the highest levels of CRP had a greater incidence of episodic memory impairment and visuospatial impairment, though no greater rate of executive function or language impairment." (PMID 40370669, 2025).
Werner syndrome (2 papers, 2016 to 2024). "A study that focused on Werner syndrome, which also predisposes individuals to accelerated aging, showed that patients had low-grade inflammation characterized by high rates of inflammatory cytokines and mediators, such as C-reactive protein (CRP), IL-6, IL-8, and TNF in their blood." (PMID 38474366, 2024).
white matter hyperintensities (2 papers, 2023). "Both higher white matter hyperintensities (WMH) and higher BMI contributed to increased deep-to-periventricular WMH ratio through elevated IL-6 rather than CRP, although CRP was in the similar tendency." (PMID 36334250, 2023).
Xanthelasma (2 papers, 2013 to 2015). The presence of xanthomata in the skin of the eyelid. "There is a need for a further study to explore the role of other markers of CAD like CIMT and high-sensitivity C reactive protein (hs-CRP) in high-risk cases of xanthelasma." (PMID 23865074, 2013). "Using Univariate logistic regression model, significant risk factors associated with the development of NAFLD were; double chin, buffalo hump, skin tag, xanthelasma, systolic blood pressure, WC, BMI, %BF, TG, fasting insulin, HOMA-IR and Hs-CRP." (PMID 26599361, 2015).
yang deficiency (2 papers, 2013 to 2022). Yang deficiency is a concept from traditional Chinese medicine. "Our results indicated that the CRP was significantly upregulated in both Yang deficiency and Qi-yin deficiency patients." (PMID 35087594, 2022). "However, like CRP protein, Cystatin C also showed a higher induced level in Yang deficiency (upregulated by 2.3-fold) than in Qi-yin deficiency (upregulated by 1.4-fold) patients." (PMID 35087594, 2022). "However, CRP protein showed a higher induced level in Yang deficiency (upregulated by 15.8-fold) compared to Qi-yin deficiency (upregulated by 8.6-fold) patients." (PMID 35087594, 2022).
21-hydroxylase deficiency (1 paper, 2024). "Fasting blood was obtained for visfatin, leptin, adiponectin, glucose, insulin, CRP, lipid panel, total cholesterol (TC), triglycerides (TG) and HbA1c, as well as standard laboratory tests to assess adrenal control, from children with CAH due to 21-hydroxylase deficiency." (PMID 39175574, 2024).
Acute hepatic failure (1 paper, 2011). Hepatic failure refers to the inability of the liver to perform its normal synthetic and metabolic functions, which can result in coagulopathy and alteration in the mental status of a previously healthy individual. "In the evaluation of patients who had affectors for CRP producibility, there were three patients (5.7%) in ALI/ARDS, and seven patients (9.9%) in CPE, who had acute hepatic failure." (PMID 21696613, 2011).
acute myelomonocytic leukaemia (1 paper, 2023). "We report the case of a man in his 50s with refractory acute myelomonocytic leukaemia (AML) who presented with neck swelling, fever, and elevated levels of C-reactive protein (CPR) after venous punctures." (PMID 36751214, 2023).
acute synovitis (1 paper, 2025). An acute inflammation of a synovial membrane. "Our previous research demonstrated the significant utility of CRP in differentiating SA from acute synovitis (AS), aligning with the previous research." (PMID 41163924, 2025).
acute tubular necrosis (1 paper, 2024). "In the acute kidney disease group, acute tubular necrosis, higher levels of C-reactive protein and reduced levels of haemoglobin and platelets increased the risk of death." (PMID 39446278, 2024).
adrenal tumor (1 paper, 2023). "Six years prior, a right adrenal tumor was detected during the examination for ovarian teratoma without C-reactive protein (CRP) elevation." (PMID 37908215, 2023).
Alkalosis (1 paper, 2024). Depletion of acid or accumulation base in the body fluids. "Laboratory tests showed elevated C-reactive protein and sedimentation rate, suggestive of inflammation, while arterial blood gas showed compensated respiratory alkalosis." (PMID 38803753, 2024).
ameloblastoma (1 paper, 2022). The most common odontogenic tumor, arising from the epithelial component of the embryonic tooth and usually affecting the molar-ramus region of the mandible or maxilla. "With these bioinformatic analyses it is possible that pathogenic ameloblastoma development involve these genes in intracellular regulation (AKT1, ACTC1, ADAM10, and APOA2) or for tumor microenvironment regulation (CRP, BCHE, APP, AGT)." (PMID 36553196, 2022).
amenorrhea (1 paper, 2020). The absence of menses in a woman who has achieved reproductive age. "Post-menopausal women (self-reported with amenorrhea), had higher median CRP concentrations (4.31 [1.72; 11.9] mg/L) than men (2.42 [0.72; 7.87] mg/L) and pre-menopausal women (3.05 [0.82; 9.00] mg/L; p < 0.0001)." (PMID 32933066, 2020).
ankle fracture (1 paper, 2020). Traumatic or pathological injury to the ankle joint in which the continuity of an ankle bone is broken. "Elevated levels of highly sensitivity CRP were closely correlated with the occurrence of DVT in ankle fracture patients before and shortly after the operation." (PMID 33239071, 2020).
anovulation (1 paper, 2017). The absence of ovulation. "Though they do not specifically investigate non-acute CRP, these studies found that higher levels of CRP are associated with anovulation and lower levels of progesterone and estrogen." (PMID 28003312, 2017).
antibody deficiency (1 paper, 2020). "Though they had significantly elevated CRP and ESR, neither had antibody deficiency nor recurrent infections, which are characteristics of APLAID (PLCG2-associated antibody deficiency and immune dysregulation) syndrome." (PMID 33042144, 2020).
Argininemia (1 paper, 2016). Arginase deficiency is a rare autosomal recessive amino acid metabolism disorder characterized clinically by variable degrees of hyperammonemia, developing from about 3 years of age, and leading to progressive loss of developmental milestones and spasticity in the absence of treatment. "Argininemia at the moment of admission correlated significantly with glutaminemia [Pearson’s correlation coefficient (r) = 69.5 %, P = 0.0001], ornithinemia (r = 55.6 %, P = 0.006), C-reactive protein (r = 71.1 %; P = 0.006) and albuminemia (r = 70.1 %; P = 0.008)." (PMID 27582779, 2016).
ascariasis (1 paper, 2017). An infection that is caused by the roundworm Ascaris lumbricoides, many cases of which remain asymptomatic. "It is possible that treatment of ascariasis may inadvertently increase CRP and that the treatment of BV may lead to the opportunistic growth of concurrent/more aggressive microorganisms and to an elevation in CRP, which could adversely affect pregnancy outcomes." (PMID 28571565, 2017).
asphyxia (1 paper, 2022). A state of general hypoxia and hypercapnia (abnormally elevated carbon dioxide (CO2) levels in the blood), resulting in acidosis, which affects all tissues in the body. "This is because, unlike physiological conditions like intra ventricular hemorrhage, stressful deliveries, fetal distress, meconium aspiration,and perinatal asphyxia, the CRP value increases and returns to normal in 24 to 48 hours." (PMID 37654832, 2022).